U8 (U8 small nucleolar RNA )
Synonyms: LOC124900197
Gene: Small nucleolar RNA gene on chromosome 5 (15,110,786 to 15,110,920, reverse strand). Ensembl gene ENSG00000202269.
Gene Ontology:
Biological process: RNA processing
Cellular component: nucleolus
Homologues: Orthologues: chimpanzee U8 (97% identical), macaque U8 (93% identical), guinea pig U8 (69% identical), rabbit U8 (59% identical), mouse Gm56239 (56% identical). Paralogues in human: U8 (84% identical), U8 (83% identical), U8 (82% identical), U8 (80% identical), U8 (78% identical), U8 (77% identical), U8 (76% identical), U8 (75% identical), U8 (74% identical), U8 (72% identical), U8 (66% identical), U8 (65% identical), and 2 more.